MITF (melanocyte inducing transcription factor)
Diseases named in the same sentence as MITF in open-access papers (continued):
Sharing a sentence is not in itself a finding about the gene and the disease.
melanoma (continued). "Additionally, MITF is a key melanocyte-specific transcription factor involved in the epithelial to mesenchymal phenotype switching involved in melanoma therapeutic resistance and proliferation." (PMID 33922284, 2021). "In addition, the AP-1 family member c-Jun is highly active in melanoma cells, and its expression is negatively regulated by MITF, which binds to the JUN promoter and blocks its transcription." (PMID 34604096, 2021). "Since our results showed HuR-NP treatment alone reduced MITF and U0126 induced MITF, we investigated whether HuR-NP can suppress MITF when overexpressed in melanoma cells analogous to that seen in melanoma patients." (PMID 33418925, 2021). "Analysis of the normalized expression data from the 479 samples in TCGA melanoma cohort (RNA-seq) showed a clear positive correlation between the expression of MITF and ADAM10 with a Spearman coefficient of 0.34 (p = 1.44e− 14) and a Pearson coefficient of 0.37 (p = 6.57e− 17)." (PMID 33789714, 2021). "In human melanocytes, MAPK signaling causes reduction of MITF and increases ERBB3, FOXD3 and NRG1 transcription factor gene expression, with NRG1 and FOXD3 also further upregulating ERBB3, which can heterodimerize with EGFR causing melanoma metastasis." (PMID 34067095, 2021). "Studies in transgenic medaka have shown that expression of Xmrk is correlated with STAT5 activation and increased expression of microphthalmia-associated transcription factor (MITF), which upregulates B-cell lymphoma 2 (Bcl-2) and surviving, and is also associated with melanoma progression." (PMID 34067095, 2021). "In melanocytes, MITF alteration seems to be an early event linked to serine/threonine-protein kinase B-Raf (BRAF) activation, which is also an early event in melanoma genesis." (PMID 34698095, 2021). "We first observed this using our MITF-KO cells but verified our observations in other cell models by overexpression and knockdown of MITF using siRNA and inducible microRNA against MITF (miR-MITF) in melanoma cells." (PMID 33438577, 2021). "As for melanomas alone, the prevalent pattern in MITF-mutated patients is the nonspecific one, including amelanotic/hypomelanotic nodular melanomas, where it can be associated with atypical polymorphic vessels." (PMID 34442055, 2021). "However, combining HuR-targeted therapy with a small molecule MEK inhibitor suppressed MITF and produced a synergistic antitumor activity against melanoma cells." (PMID 33418925, 2021). "In line with our initial observations, only a minority of the cases (12/125; 9.6%) could be explained by a clinically validated pathogenic variant in one of the two known genes predisposing to both melanoma and RCC, namely MITF (N = 9) and BAP1 (N = 3)." (PMID 34067022, 2021). "Indeed, in melanoma MiTF is generally overexpressed, with gene amplification observed in approximately 30% of the samples, or overactivated by phosphorylation in a B-RAFV600E/ERK-dependent manner." (PMID 33441180, 2021). "Lastly, IL-1β can upregulate HIF1α, known to inhibit MITF and increase melanoma invasiveness." (PMID 34604096, 2021). "BRN2 is known to transcriptionally repress MITF and potentially contribute to the high mutational burden of melanoma through promoting the more error-prone non-homologous end-joining DNA repair system." (PMID 35008286, 2021). "SP has been reported to have anti-inflammatory effect and antioxidant effect, When B16F10 melanoma cells were treated with 0–50 μm SP, it was found that SP to induce melanin synthesis in a dose-dependent manner by increasing the expression of MITF and tyrosinase via increasing CREB phosphorylation." (PMID 34858164, 2021).
melanoma (continued). "Since expression of MLANA, a differentiation-associated melanosomal protein, is regulated by MITF, our results suggested that irradiation might also induce MITF expression, and that MITF could play a role in immune recognition of melanoma cells." (PMID 33789714, 2021). "MITF is considered to be the master regulator of melanocytes and an oncogene in melanoma." (PMID 33746605, 2021). "Indeed, we observed changes in important EMT markers and regulators such as ZEB1, CDH1 (E-Cadherin), CDH2 (N-Cadherin), SNAI2, and TGFß1 in the MITF-KO cells as well as in TCGA melanoma samples." (PMID 33438577, 2021). "Since MITF expression and activity are regulated by the various signaling pathways, the tumor microenvironment has been proposed to instruct phenotypic changes in melanoma cells and thus foster disease progression." (PMID 33438577, 2021). "In a study investigating the prognostic and predictive values of oncogenic BRAF, NRAS, c-KIT, and MITF in melanoma, it was found that initial lymph node involvement was more frequent in patients with BRAF-mutated melanomas, than in cases presenting other mutations." (PMID 34209415, 2021). "Our studies suggest that downregulation of MITF may constitute one of the critical molecular events that drive melanoma growth." (PMID 33803640, 2021). "On the one hand, MITF is amplified in melanoma metastases and patients with MITF amplifications have poorer survival, indicating that MITF may act as an oncogene." (PMID 34071193, 2021). "Interestingly, the TME and stiffness of the extracellular matrix (ECM) have been shown to impact MITF expression levels in melanoma, and TGF-β is also partly involved in this regulation." (PMID 34071193, 2021). "Reduction of MITF activity sensitizes melanoma cells to therapeutic agents." (PMID 34289891, 2021). "Direct targeting of MITF with small molecule inhibitors has proven to be a challenge; however, indirect suppression of MITF through histone deacetylase inhibitors has been shown to reduce MITF mRNA expression in melanoma." (PMID 33807778, 2021). "Melanoma cells that highly express MITF can differentiate or proliferate." (PMID 34784909, 2021). "Similar to β-catenin, previous studies demonstrated that HINT1 could also interact with and repress the function of MITF, which has been well known as a master regulator of melanocyte development and function, in activated mast and melanoma cells." (PMID 32636443, 2020). "Mechanistically, T cell-driven inflammatory stimuli such as TNF-α, engage the transcription factor c-jun in tumor cells, which in turn reduces MITF levels, and consequently decreases the expression of melanocyte differentiation genes, thereby leading to melanoma cell dedifferentiation." (PMID 33276788, 2020). "Whether and how SMS1 downregulation and the consequent SL metabolism alterations modulate MITF and melanoma progression remains to be investigated." (PMID 33121001, 2020). "Since ACF decreased glucose availability and affected the HIF-1α pathway under normoxic conditions, we hypothesized that the induction of an ER stress response pathway could be responsible for the ACF-dependent suppression of MITF in melanoma cells." (PMID 33396270, 2020). "Since MITF contributes to high invasive and migratory potential in melanoma and renal carcinoma, we examined whether the same was true in OvCa." (PMID 33371469, 2020). "Furthermore, a recent paper interestingly reported a strong correlation of the expression of SR-BI with MITF expression as well as with the melanin synthesis pathway in human melanoma cells." (PMID 32093380, 2020).
melanoma (continued). "Finally, using a ChIP-Seq database, AC was identified as a direct target of MITF, demonstrating that MITF and AC are part of a positive feedback loop that controls melanoma plasticity." (PMID 33121001, 2020). "Thus, SK-MEL-1 cells express basal levels of MITF, and it is generally accepted that melanoma cells with high amounts of this transcription factor are less vulnerable to ROS." (PMID 32674468, 2020). "Our regulatory genomics analysis of LTR5_Hs loci indicates that Melanocyte Inducing Transcription Factor (MITF) (also known as binds to a canonical E-box motif (CA(C/T)GTG) within these elements in proliferative type of melanoma, and that depletion of MITF results in reduced HERV-K expression." (PMID 33202765, 2020). "Secondly, AC ablation by the CRISPR-Cas9 technology, which is associated with the accumulation of long-chain saturated ceramides, led to a strong downregulation of MITF expression in human A375 melanoma cells, reducing their ability to form cancer-initiating cells and to undergo self-renewal." (PMID 32858889, 2020). "Consequently, MITF has been shown to suppress melanoma metastasis through its transcriptional activation of miR-211 via the TRPM1 promoter." (PMID 33003444, 2020). "Considering only melanomas, the prevalent pattern among the MITF+ patients was the unspecific one, a finding that has never been associated with the MITF+ variant to date." (PMID 32054529, 2020). "Accumulating evidence indicate that AXL is a marker of invasive phenotype in melanoma, linked to the absence of microphthalmia-associated transcription factor (MITF) and the expression of an EMT signature." (PMID 33203881, 2020). "Moreover, low activity of stearoyl-CoA desaturase (SCD), which catalyzes the rate-limiting step of FA desaturation, reduced MITF expression and maintained melanoma cells in an MITF-low de-differentiated state." (PMID 33121001, 2020). "MITF expression is also essential for melanoma cell proliferation and survival." (PMID 33614507, 2020). "Publicly available ChIP-seq data for MITF in 501Mel and Colo829 human melanoma cells were analyzed in order to determine if MITF might be involved in directly regulating its own expression or that of TFEB and TFE3." (PMID 32881934, 2020). "Importantly, MITF can act as an amplified oncogene in a fraction of human melanomas and that it also has an oncogenic role in human clear cell sarcoma." (PMID 32397616, 2020). "Interestingly, a review showed that MITF plays an important role in migration and invasion in melanoma cells." (PMID 33371469, 2020). "High MITF level is found in more than 20% of melanomas following MAPK inhibitor treatment." (PMID 32626712, 2020). "Moreover, leaf extracts demonstrated ERK pathway activation and downregulation of MITF and tyrosinase and, therefore, a decrease in melanogenesis in B16 melanoma F10 cells." (PMID 33322185, 2020). "However, the genes ANXA1, PDGFC, VEGFC and LRRN3 were downregulated in CL1-0 shMITF-harboring cells, while they were upregulated in si-MITF melanoma 501MEL cells." (PMID 33293474, 2020). "MITF is a melanoma oncogene and plays a central role in melanoma progression." (PMID 33371469, 2020). "In mouse melanoma cells Rb1 cooperates with MITF to activate expression of Tyr and Cdkn1a/p21Cip1." (PMID 32850962, 2020). "Furthermore, MITF is also a key determinant of melanoma cell plasticity and tumor heterogeneity, which are undoubtedly one of the major hurdles for an effective immunotherapy." (PMID 33276788, 2020). "Together, these observations delineate that MYC and CTNNB1 may act as immune exclusion molecules in MITF‐positive melanoma tumors." (PMID 32147909, 2020).
melanoma (continued). "We highlight how MITF, by controlling differentiation and genome integrity, may regulate melanoma-specific antigen expression by interfering with the endolysosomal pathway, KARS1, and antigen processing and presentation." (PMID 33276788, 2020). "MITF function has been tightly connected to melanoma cell plasticity." (PMID 32858889, 2020). "Naive melanoma cells exposed to the inflammatory secretome of MITF-depleted cells switch towards a dedifferentiated phenotype with a reduced immunogenicity ability that could contribute to escape from immune responses." (PMID 33276788, 2020). "Finally, the activation of both MEK/ERK pathway and MITF mediates the formation of the resistance to BRAFi in melanoma cells." (PMID 32532957, 2020). "The Wnt/β-catenin pathway is a well-known activator of MITF expression in melanoma cells, and deactivation correlates with a higher metastatic potential, suggesting a role of the Sphk1/S1P axis in melanoma aggressiveness through MITF downregulation via the Wnt/β-catenin pathway." (PMID 33121001, 2020). "In addition, the activation of LXRs by the synthetic ligand TO901317 potently inhibited melanogenesis through ERK-induced MITF degradation in human primary melanocytes and B16 melanoma cells." (PMID 33121001, 2020). "On one hand, inactivation of AKT by ACF may be important to maintain the stability of MITF in melanoma cells." (PMID 33396270, 2020). "The decrease of melanoma cell growth, together with the evidence of high toxicity, cell cycle arrest, and MITF pathway inhibition, suggested that HCOE could induce cell death." (PMID 33080917, 2020). "The survival associated mitochondrial melanoma specific oncogenic non-coding RNA (SAMMSON) maps to human chr3p13, a region amplified in 10–15% of human melanomas that also hosts the transcription factor MITF, the master regulator of melanocyte and melanoma biology." (PMID 33142861, 2020). "It would also be interesting to find out whether Rec overexpression can lead to enhanced MITF expression in invasive melanoma, and revert the invasive phenotype to a proliferative one." (PMID 33202765, 2020). "The phenotype of SK-MEL-28 melanoma cells was altered as MITF expression was decreased." (PMID 32850759, 2020). "Together, these data suggest that MITF may be orchestrating the effects on melanoma cell differentiation and proliferation induced by osteoblasts." (PMID 31323160, 2020). "In melanoma cells, growth is promoted by altering expression of MITF (melanocyte inducing transcription factor), although an opposite effect of invasion-blocking MITF mediated has been observed." (PMID 32850962, 2020). "Importantly, we observed a significant decrease in H3K4me3 enrichment at the melanoma-associated genes, CD271, AXL, SOX10, and MITF." (PMID 32620791, 2020). "Furthermore, we searched for genes that had a significant correlation with MITF expression in lung adenocarcinoma or melanoma." (PMID 33293474, 2020). "Several studies have investigated the potential of MITF in specificity and sensitivity in distinguishing melanoma from other cancers, however, the discovery of the presence of MITF in other non-melanocytic cell types in the tumor microenvironment has complicated this notion." (PMID 33614507, 2020). "MITF(M) is a critical transcription factor associated with melanoma progression, and is a sensitive marker of melanoma invasiveness: it is highly expressed (e.g., MITF-High) in the melanocytes and the proliferative state of melanoma, but lowly (e.g., MITF-Low) expressed in the invasive state." (PMID 33202765, 2020). "The distinct functions of MITF in lung adenocarcinoma and melanoma attracted our interest." (PMID 33293474, 2020). "Thus, we believe that our results will require confirmation in a further larger epidemiological study in our population and others, and quantitative and functional analyses of ADCY3, CREB1 and MITF SNVs in melanoma cells." (PMID 32699307, 2020).
melanoma (continued). "The expression ratio of MITF/AXL has been used to describe early resistance in melanoma." (PMID 33167306, 2020). "In contrast, quercitrin modulated the ERK and MITF signalling pathway in B16F10 melanoma cells." (PMID 33322185, 2020). "In addition, AC overexpression in melanoma cells decreased tumour cell motility, whereas AC silencing had the opposite effect, as was observed for MITF." (PMID 32858889, 2020). "Mechanistically, low SCD expression and activity promoted ER stress and the phosphorylation of eukaryotic initiation factor-α (eIF2α) leading to the activation of an ATF4- and NF-κB-dependent inflammatory signaling that sustains a reduced MITF expression and melanoma cell dedifferentiation." (PMID 33121001, 2020). "To test our hypothesis, we focused on MITF and SOX10 as the two most essential TFs in skin and used the A375 melanoma cell line harbouring the BRAF activating mutation." (PMID 33073517, 2020). "Interestingly, another transcription factor that is related to TFEB, microphthalmia-associated transcription factor (MITF) has been shown to bind to the promoters of genes encoding lysosomal and autophagosomal proteins in melanoma." (PMID 32340261, 2020). "MITF+ were more likely to develop dysplastic nevi and multiple primary melanomas." (PMID 32054529, 2020). "Our results are contradictory to these findings as: (i) TYRP1 expression was similar in MITF-Mlow and MITF-Mhigh melanoma cells and (ii) MITF-M loss accompanying the development of drug resistance in MITF-Mhigh cells, did not influence TYRP1 expression." (PMID 31624899, 2020). "Conversely, resistance to MEK inhibition in NRAS-mutant melanoma may be mediated through activation of the anti-apoptotic cAMP/MITF/Bcl-2 pathway." (PMID 32517051, 2020). "Studies have also shown that decreased expression of melanocyte differentiation antigens through downregulation of MITF could possibly trigger immune evasion in melanomas." (PMID 32147909, 2020). "Together these results suggest the existence of a regulatory loop between MITF and Rec that may modulate the transition from proliferative to invasive stages of melanoma." (PMID 33202765, 2020). "In addition to expression of AXL, NGFR and a lineage-specific transcription factor MITF, expression of SOX transcription factors that are associated with control of cancer cell plasticity, is broadly used to classify the phenotypes of melanoma cells." (PMID 31936151, 2020). "In addition, the long-term reduction of MITF in melanoma cells leads to the induction of cellular senescence." (PMID 32455577, 2020). "In addition to its effect on proliferation, melanoma cells low in MITF also show strong resistance to multiple targeted drugs against melanoma." (PMID 32899370, 2020). "Thus, a previous report has suggested that the pro-angiogenic response of melanoma to low levels of oxygen depends at least in part on HIF-1α mediated downregulation of MITF." (PMID 33396270, 2020). "When compared to the overall expression of other TE families, LTR5_Hs/HERV-K was the most abundantly expressed TE family and showed the strongest positive correlation with MITF levels (rho = 0.43, corrected p-value < 0.2 × 10−9) in the melanoma primary cultures (N = 10)." (PMID 33202765, 2020). "Although, MITF favors melanoma proliferation, it might be worth evaluating the effects of agents that increase MITF expression on the response to ICT." (PMID 33276788, 2020). "However, in vivo endogenous MITF can be transcriptionally downregulated in xenograft tumors as well as in human melanoma." (PMID 32531202, 2020).